CGAS (cyclic GMP-AMP synthase)
Diseases named in the same sentence as CGAS in open-access papers (continued):
Sharing a sentence is not in itself a finding about the gene and the disease.
tumor (continued). "Therapeutic interventions that increase tumor DNA damage can potentiate cGAS-STING–mediated immunity." (PMID 40981069, 2025). "Collectively, these data are consistent with a model wherein chemotherapy induced DNA damage can drive both G2/M cell cycle arrest and cGAS-STING mediated inflammatory signaling responses in SCLC tumor cells." (PMID 40114214, 2025). "Inducing tumor cell apoptosis or necrosis provides another method of triggering the cGAS-STING pathway." (PMID 40052963, 2025). "Initially identified as a defense mechanism against viruses, the cGAS-STING pathway has recently been recognized for its critical role in anti-tumor immunity 5,13." (PMID 40520004, 2025). "Activation of the cGAS-STING pathway induces an immune pro-inflammatory response effectively triggering an anti-tumor T cell response." (PMID 41246345, 2025). "Recently, it has been reported that cDC1s are activated through the DNA sensing pathway involving cGAS/STING in both tumor-bearing mice and cancer patients." (PMID 39842944, 2025). "In summary, cGAS–STING activation can not only facilitate tumour immune evasion but also induce a hyperinflammatory state." (PMID 41275427, 2025). "In DCs, tumor-derived DNA can be internalized via exosomes, which activate cGAS-STING and promote the production of IFN-I, the maturation of DCs, the up-regulation of MHC-I and the suppression of lysosomal degradation of tumor antigens." (PMID 40849659, 2025). "Subsequently, we evaluated the cGAS‐mediated synthesis of cGAMP and found that following the internalization of dsDNA released from tumor cells after RT, the cGAMP levels within L929 cells markedly increased." (PMID 39976106, 2025). "In our study, the CDH11 inhibitor specifically targeted hybrid EMT tumor cells and activated the cGAS‐STING pathway, Thereby, the induction of apoptosis in these cells simultaneously stimulates immune cell activation." (PMID 39739317, 2025). "Concurrently, REV activated the cGAS-STING pathway, repolarizing tumor-associated macrophages (TAMs), expediting dendritic cell immunogenic maturation, and enhancing cytotoxic T-lymphocyte infiltration, thereby achieving tri-modal immuno-therapeutic synergy." (PMID 40429976, 2025). "The combination of YAP1 inhibitor, verteporfin and DDP enhances anti-tumor immunity by regulating the interaction between YAP1 and cGAS-STING in the tumor microenvironment, providing new insights into a combined chemotherapy strategy for HCC." (PMID 40918140, 2025). "Elucidating which alternative cytosolic DNA-sensing mechanism is activated after PARP trapping in cGAS-STING–defective tumor cells is an area for further research." (PMID 39851178, 2025). "An activation of cGAS-STING signaling in tumor cells stimulates the expression of many ligands of the inhibitory immune checkpoint receptors, such as PD-L1, and thus provides a route for immune evasion by tumor cells." (PMID 41241888, 2025). "All these products contribute to the ICD of tumor cells, stimulating the cGAS-STING pathway, activating DCs, increasing T lymphocytic infiltration, and reversing the immunosuppressive microenvironment (shifting from M2 macrophages to M1 macrophages)." (PMID 40435257, 2025). "This review targets recent advancements in nanomaterials of enhancing cGAS-STING-mediated anti-tumor immune responses." (PMID 40831989, 2025). "Activation of the cGAS-STING pathway plays a key role in the induction of the anti-tumor response through production of type I interferons, maturation of dendritic cells (DCs), and recruitment of cytotoxic T cells (CD8+)." (PMID 41007722, 2025). "The correlation between cGAS-STING activation and tumor metastasis has spurred further assessment and exploration of STING agonists in tumor treatment, highlighting the intricate roles of cGAS-STING in tumors." (PMID 40075527, 2025). "Upon tumor accumulation, bacterial dsDNA cargo within OMVs directly activated the cGAS-STING axis in tumor cells, inducing ICD." (PMID 41035884, 2025).
tumor (continued). "Activation of the cGAS‐STING signaling pathway can transform a ‘cold’ tumor microenvironment into a ‘hot’ one by stimulating interferon (IFN) production, offering a promising avenue to enhance immunotherapy against malignant tumors." (PMID 39834553, 2025). "There is emerging evidence that ZnO-NPs can stimulate an immunogenic form of tumor cell death (via pathways like cGAS-STING), suggesting a potential role in cancer immunotherapy when used in combination with other agents, beyond chemotherapeutics." (PMID 40943339, 2025). "In UPCI:SCC090 tumor cells, cGAS and STING were upregulated post-IR, consistent with in vitro data, and their levels were significantly higher than in HPSCC models." (PMID 41401057, 2025). "Once it reaches the tumor, it activates the cGAS-STING pathway, induces ICD, and simultaneously blocks the PD-1/PD-L1 axis due to the presence of the aPD-1 antibody." (PMID 41007722, 2025). "While acute activation of the cGAS-STING pathway supports antiviral defense, tumor surveillance, and responses to genotoxic stress, chronic cGAS-STING activation can lead to endoplasmic reticulum stress, thereby promoting immune evasion and metastasis." (PMID 41193733, 2025). "Radiotherapy, oncolytic viral therapy, and cancer vaccines increase tumor-specific antigen availability, whereas cytokines and cGAS-STING agonists enhance antigen processing and APC activation." (PMID 40325301, 2025). "Overall, our data suggest that BF839 enhanced tumor sensitivity to ICIs through cGAS-STING signaling." (PMID 40231233, 2025). "The T cell abundance and tumor-T cell interactions in different CGAS and STING1 expression groups were analyzed using bulk RNA-seq and scRNA-seq data from open databases." (PMID 40735041, 2025). "Our study elucidates a crucial underlying mechanism: LPS perturbs the precisely coordinated STING-mediated anti-tumor immune response by reducing tumor cell sensitivity to cytosolic DNA and elevating the activation threshold of the cGAS-STING pathway." (PMID 41235258, 2025). "Beyond antiviral defense, the cGAS–STING pathway has emerged as a crucial mediator of anti-tumor immunity." (PMID 41007722, 2025). "Mn2+, when combined with tumor-disrupting adjuvants, forms antitumor nanoregulators that cascade-activate the cGAS-STING pathway, thereby enhancing immunotherapeutic efficacy against cancer." (PMID 41438738, 2025). "Mechanistically, radiotherapy-induced tumor cell–derived microparticles containing dsDNA activated the cGAS-STING/NF-κB signaling pathway in macrophages, upregulating the expression of the chemokine CCL20, which was critical for γδ T cell recruitment." (PMID 41055972, 2025). "Mechanistically, we reveal that OMVs act as natural STING agonists: their intrinsic bacterial dsDNA cargo directly activates the cGAS‐STING pathway in cancer cells, potentially in tumour‐associated macrophages (TAMs) upon phagocytosis." (PMID 40240911, 2025). "Radiotherapy can remodel the tumor microenvironment (TME) via cGAS–STING/I-type interferon signaling, enhancing tumor neoantigen presentation, dendritic cell maturation, CD8+ T-cell infiltration, and M1 macrophage polarization." (PMID 41302177, 2025). "More importantly, several strategies of targeting cGAS-STING for reprogramming TAMs were designed for enhancing anti-tumor immunotherapy." (PMID 40075527, 2025). "The ongoing clinical trials investigating combination therapies that target the cGAS-STING pathway highlight the growing significance of DNA damage induction in shaping effective tumor immunotherapy strategies." (PMID 40333779, 2025). "This pathway is initiated when cyclic GMP-AMP (cGAMP) synthase (cGAS) recognizes DNA released from dying tumor cells." (PMID 40761260, 2025). "Within the tumor microenvironment, the cGAS-STING pathway serves as a communication channel between tumor cells and immune cells, functioning in a non-cellular autonomous manner." (PMID 40385487, 2025).
tumor (continued). "High-resolution studies demonstrate that micronuclei formation and cGAS–STING activation occur in spatially restricted tumor regions enriched for replication stress and chromosomal instability." (PMID 41373427, 2025). "↑CD8+ T anti-tumor immunity through stimulating cancer cell-autonomous type I interferon induction via ROS-triggered oxidized mtDNA sensing by cGAS-STING." (PMID 40552295, 2025). "Methionine restriction blocks cGAS methylation, which enhances its cytoplasmic localization and strengthens anti-tumor immunity." (PMID 40018041, 2025). "Further, Mn2+ in synergy with mild hyperthermia activates the cGAS-STING immune pathway for tumor immunotherapy." (PMID 39897548, 2025). "In particular, the activation of the cyclic GMP-AMP synthase (cGAS)-STING pathway by cytosolic tumor DNA is essential for the formation of antitumor T effector cells and the efficacy of ICB therapy in preclinical cancer models." (PMID 41155765, 2025). "One common mechanism is the loss or mutation of cGAS or STING, which prevents the tumor cells from activating the immune response even when cytosolic DNA is present." (PMID 40739089, 2025). "The cGAS‐STING signaling pathway has garnered significant attention as a key innate immune pathway that plays a crucial role in tumor initiation and progression." (PMID 39834553, 2025). "Tumor-derived exosomes can carry dsDNA into DCs, triggering cGAS–STING activation, which promotes IFN-I secretion and elevates CD40, CD80, and CD86 expression, ultimately promoting T cell responses." (PMID 41204180, 2025). "In in vitro models, they demonstrated that radiation-induced tumor cell–derived microparticles (RT-MPs) containing double-stranded DNA (dsDNA) upregulated the cGAS/STING/NF-κB pathway in macrophages to stimulate CCL20 production." (PMID 41392975, 2025). "The article outlines cGAS/STING’s influence on tumor microenvironments, immune surveillance, and inflammation, with emphasis on molecular mechanisms driving cancer progression." (PMID 39949780, 2025). "The cGAS-STING signaling pathway can remodel the RT-induced tumor immune microenvironment and induce type I IFNs to activate immune responses, resulting in the cellular production of proinflammatory cytokines." (PMID 41368644, 2025). "In contrast to free adjuvants, the inherent nanosize effect enables PBNPs to act as immunoadjuvant that activates the cGAS-STING pathway through photothermal damage to the endogenous DNA of the tumor cells or as NC for delivering immunoadjuvants." (PMID 40033359, 2025). "To observe the direct effect of CAFs on tumor cell-intrinsic cGAS–STING expression in CRC, we established primary CAFs from CRC specimens and co-cultured them with CRC cell lines in vitro." (PMID 40451897, 2025). "When these proteins were depleted in DLBCL and other tumor cell lines, heterochromatin redistribution, replicative stress, and cGAS–STING pathway activation occurred, which in turn triggered an inflammatory response mediated by interferon." (PMID 41155227, 2025). "Tumor cell-derived dsDNA-containing microparticles activate macrophage cGAS-STING pathway, inducing CCL20 to recruit IL-17-producing γδ T cells, driving radioresistance." (PMID 41055972, 2025). "Addressing these gaps is essential for understanding how the cGAS-STING pathway can be modulated for tumor suppression." (PMID 40362284, 2025). "In tumor cells, the cGAS-STING pathway mediates the production of interferons and proinflammatory factors, thereby enhancing the recruitment and activation of immunocytes in the tumor-microenvironment." (PMID 41409301, 2025). "Mechanistically, we revealed that engineered OMVs directly induced activation of cGAS‐STING pathway in tumour cells and potentially in TAMs." (PMID 40240911, 2025).
tumor (continued). "Within the TME, microorganisms can enhance anti-tumor immunity by activating the cGAS-STING signaling pathway." (PMID 41450920, 2025). "In subcutaneous tumor models, cGAMP-mediated immune responses require tumor-expressed cGAS and host-expressed STING, whereas tumor-expressed STING and host-expressed cGAS are dispensable." (PMID 41419196, 2025). "In line with the increased tumor debris uptake, the cGAS-STING-IFN pathway resulting in increased Il12p40 mRNA expression was also induced in iDCs lacking FX expression or FXa-PAR2 signaling." (PMID 40694429, 2025). "In hypoxic circumstances, tumor cells suppress cGAS pathway activity due to JNK1/2-mediated phospho-PCK1 which interacts with cGAS and then competes for GTP binding." (PMID 40831989, 2025). "Specifically, the cGAS–STING pathway promotes tumour resistance through downstream TBK1–IRF3/p65 NF‐κB signalling." (PMID 41275427, 2025). "Emerging evidence positions the cyclic GMP–AMP synthase (cGAS)–stimulator of interferon (IFN) genes (STING) pathway as a viable target in tumour immunotherapy, given its pivotal function in facilitating T lymphocytes." (PMID 41275427, 2025). "While cGAS-STING activation regulates type I interferon signaling, enhancing the innate immune response and anti-tumor immunity, downregulation of cGAS-STING promotes immune escape in cancer cells." (PMID 40563638, 2025). "This duality is influenced by factors such as tumor type, the spatial and temporal activation of cGAS-STING, and the surrounding tumor microenvironment." (PMID 39949780, 2025). "The integration of NMs with the cGAS-STING pathway presents transformative possibilities for tumor immunotherapy." (PMID 40831989, 2025). "These nanomaterials leverage their unique physical and chemical properties for targeted delivery, controlled release, and biodegradability, significantly improving the anti-tumor effects through synergistic activation of the cGAS-STING pathway." (PMID 40831989, 2025). "Mitochondrion-targeting drugs can induce tumor mtDNA oxidation and release to the cytoplasm, activate the cGAS-STING pathway, while mitochondrion Lipid peroxidation and ROS can also promote mtDNA release." (PMID 41246345, 2025). "Induces oxidation of tumor mitochondrial DNA, translocates to APCs, activates cGAS-STING signaling, and triggers potent anti-tumor T cell immunity." (PMID 41246345, 2025). "For instance, miRNAs like miR-25 and miR-93 suppress cGAS expression, facilitating tumor progression, while others like miR-27b-3p dampen STING activity to mitigate inflammation." (PMID 39949780, 2025). "For effective antitumor immune responses, the induction of the cGAS-STING-IFN-I pathway that is driven by the uptake of tumor-derived nucleic acids plays a major role." (PMID 40694429, 2025). "In this study, we engineered PEI and CpG as adjuvants on the surface of MnO2-mineralized tumor cells to leverage the synergistic activation of the cGAS-STING and multivalent TLR pathways for immune modulation." (PMID 40291558, 2025). "These nanoparticles were internalized by tumor cells, inducing the release of mtDNA and nuclear DNA, which then transferred to DCs to initiate cGAS–STING signaling." (PMID 41049749, 2025). "Methionine deficiency can reduce the methylation of cGAS, prompting its translocation from the nucleus, thereby activating the cGAS-STING pathway and exerting anti-tumor immune effects." (PMID 40739140, 2025). "SAM also attenuates the activation of the STING pathway by promoting the methylation of cyclic GMP-AMP synthase (cGAS), resulting in a weakened anti-tumor immune response." (PMID 40018041, 2025). "Targeting cGAS-STING pathway for reprogramming TAMs shows promise in enhancing anti-tumor immunotherapy." (PMID 40567603, 2025). "Since chronic inflammation contributes to tumor progression, anti-inflammatory treatments can help reverse the protumor effects of cGAS-STING activation." (PMID 40052963, 2025).
tumor (continued). "The cyclic GMP-AMP synthase (cGAS)/stimulator of IFN genes (STING) pathway is intimately associated with antitumoral immunity; however, the direct involvement of this pathway in tumor cell demise remains elusive." (PMID 40663398, 2025). "Cancer cell-intrinsic type I IFN levels were also dramatically increased by radiation and CHK1 inhibition through the cGAS/STING axis, which in turn reshaped the tumor microenvironment within ARID1A-deficient tumors." (PMID 40750787, 2025). "Cyclic GMP-AMP synthase (cGAS) can recognize exogenous DNA (bacterial viruses, dead cells, tumor cells, etc.)and endogenous DNA (damaged chromosomes, mitochondria, etc.)and bind to the obtained double-stranded DNA (dsDNA) to form cyclic GMP-AMP (cGAMP)." (PMID 41268564, 2025). "Such strategies are typically based on paradigms of increasing the tumor mutational burden (TMB) and resulting tumor-associated neoantigens, or increasing type I IFN expression through nucleic acid–driven cGAS/STING activation." (PMID 40663394, 2025). "Radiotherapy-induced DNA damage can lead to apoptotic cell death and trigger an anti-tumor immune response via the cyclic GMP–AMP synthase–stimulator of interferon genes (cGAS–STING) pathway, which senses cytoplasmic double-stranded DNA." (PMID 40355720, 2025). "For example, a study conducted in 2024 showed that Svg3, a nature-inspired oligonucleotide, is a potent cGAS agonist that activates cGAS-STING in tumor immunotherapy." (PMID 40104511, 2025). "In the absence of cGAS or when its function is impaired, the efficacy of immune checkpoint inhibition therapy is significantly diminished, suggesting that the presence of cGAS is a crucial factor in the success of tumor immunotherapy." (PMID 41226461, 2025). "Mechanistically, when double-stranded DNA (dsDNA) originating from pathogens, injured host cells, or tumor-derived micronuclei is detected, cGAS facilitates the production of the second messenger 2’3’-cyclic GMP–AMP (2′3′-cGAMP) using ATP and GTP." (PMID 41204180, 2025). "Activation of the cGAS-STING pathway upregulates the pro-apoptotic protein BAX while simultaneously reducing the expression of the anti-apoptotic protein BCL2 in tumor cells." (PMID 40006729, 2025). "SBGC can also enhance anti-tumor immune responses and induce long-term T-cell memory by activating the cGAS-STING pathway and PD-L1 immune checkpoint blocking." (PMID 39897548, 2025). "In cancer, the cGAS-STING pathway detects DNA released from tumor cells undergoing apoptosis or necrosis." (PMID 40739089, 2025). "The released tumor mitochondria DNA triggers the cGAS-STING pathway activation and enhances T cell immunity." (PMID 40643531, 2025). "Recent efforts have focused on enhancing anti-tumor immunity by targeting innate immune responses within tumors, with particular attention to the cGAS-STING signaling pathway." (PMID 39994264, 2025). "In conclusion, the mouse tumor-bearing model verified that knockdown of OASL enhanced the activation of the cGAS-STING signaling pathway and enhanced OXA-induced ICD in GC cells,thus increasing the sensitivity of OXAchemotherapy." (PMID 41271618, 2025). "Given the genomic instability or oxidative stress observed in tumor cells, DNA leakage frequently occurs, triggering the activation of the cGAS-STING within the cytoplasm." (PMID 40075527, 2025). "These engineered OMVs function as natural stimulator of interferon genes (STING) agonists, activating the cyclic GMP‐AMP synthase (cGAS)‐STING pathway in cancer cells and tumour‐associated macrophages (TAMs)." (PMID 40240911, 2025). "On the other hand, methionine flux also supports the cancer cells to escape from cyclic GMP-AMP synthase (cGAS) mediated anti-tumor immunity in the methylation dependent manner." (PMID 41445748, 2025).